CD14 (CD14 molecule)
Diseases named in the same sentence as CD14 in open-access papers (continued):
Sharing a sentence is not in itself a finding about the gene and the disease.
tumor (continued). "Sampling of early-stage tumours suggested that tumour CD14+ cells were not primarily immunosuppressive against T cell cytokine production or proliferation." (PMID 39746898, 2025). "Similarly, analysis of data from patients with CRC in TCGA and GEO databases showed that CD14, CD163, and CD206 expressions were higher in peritumor intestine than in tumor." (PMID 40756343, 2025). "It was speculated in another Mendelian randomization study that CX3CR1 on CD14+ CD16- monocytes may promote the onset of PC through the CX3CR1/CX3CL1 signaling pathway, which is actively involved in promoting tumor angiogenesis, migration, and infiltration." (PMID 40564200, 2025). "After that, the HLA-DR+CD14+CD66b+ monocytes were measured in PB (11.9 ± 2.4%), non-tumor tissue (7.5 ± 1.8%), and tumor tissue (21.1 ± 2.1%)." (PMID 40731885, 2025). "The HLA-DR + CD14+ monocytes were measured in PB (47.13 ± 3.3%), non-tumor tissue (5.06 ± 1.3%), and tumor tissue (17.08 ± 2.3%) (p < 0.001)." (PMID 40731885, 2025). "The presence of CD14pos PMNs in both cancer and non-cancer inflammatory conditions suggests that CD14 expression on tumour-infiltrating neutrophils reflects a broader inflammation-associated phenotype." (PMID 41274118, 2025). "However, several cancer-specific investigations observed an in vitro tumour microenvironment phenomenon where DC2s shifted towards a DC3 like-phenotype, acquiring CD14 and CD163 expression, in response to tumour-derived factors including IL-6 and M-CSF." (PMID 39861894, 2025). "Additionally, CD33+CD14− PMN‐MDSC levels increased in patients with larger tumors, whereas CD11b+CD14+/CD33+CD14+ M‐MDSC levels decreased in those with lymphatic tumor emboli." (PMID 39749673, 2025). "However, we previously showed that myeloid-specific proteins CD14, CD68, and PU-1 are intracellularly expressed in LYVE-1+ tumor vessels, suggesting their full merging with myeloid cells." (PMID 40507286, 2025). "CD14+CD16+ monocytes exhibit Tie 2 expression, representing an angiopoietin receptor (Tie 2/Tek) present in the human peripheral blood monocytes with notable tumor-promoting and proangiogenic properties." (PMID 41142828, 2025). "Among non-T cell populations, MPE was enriched for CD14+CD16+ monocytes (59.3% in MPE vs. 27.4% in blood vs. 1.9% in tumor)." (PMID 41415427, 2025). "While the monocyte population (CD45+CD14+) remained unchanged between healthy and non-treated tumor-bearing dogs, corticosteroid treatment markedly increased this population, consistent with its role in enhancing monocyte recruitment or survival." (PMID 40342421, 2025). "The correlation between PanCK and CD14/APOE was −.085/.098, indicating no significant relevance of CD14/APOE with tumour cells." (PMID 39187937, 2024). "Demonstrating the ability of VX-765 to induce an immunoreactive TIME within human tumors, treatment of humanized mice bearing MDA-MB231 xenografts decreased CD14+ HLA-DR+ macrophages and increased activated granzyme B positive (GrB+) CD8+ T cells, with a trend (p = 0.1) towards decreased tumor size." (PMID 39353903, 2024). "We analysed CD14+ and JCHAIN+ spots across six samples and found that pro‐tumour pathways, including angiogenesis, extracellular matrix (ECM) receptor interaction and Vascular endothelial growth factor (VEGF) signalling, were enriched in CD14+ spots." (PMID 39187937, 2024). "We also observed an increased infiltration of other cellular phenotypes such as F4/80+CD80+ M1 macrophages, CD11c+ dendritic cells, CD14+ monocytes and CD19+ B cells in the tumor of SLV group when compared with other control conditions such as no treatment (B16-OVA) and BLV groups." (PMID 38173045, 2024). "Through immunohistochemical staining with CD206 and CD66b, as well as flow cytometric analysis of CD68 + CD206+ (M2 macrophages) and CD14 + CD66b+ (neutrophils), we found that BNST tumor samples exhibited a higher accumulation of M2 macrophages (M2 mac) and a lower presence of neutrophils (neu)." (PMID 38331905, 2024).
tumor (continued). "In summary, while our study offers significant insights into the spatial structure and functional characteristics of CD14+APOE+ cells and MMP7+ tumour cells in NSCLC, additional research is needed to address these limitations and to further elucidate the mechanisms underlying therapy resistance." (PMID 39187937, 2024). "For example, CD14+CD206+ macrophages in the brain metastasis perivascular space can potentially confine immune cells to the space around blood vessels and prevent cells such as T cells from accessing the tumor." (PMID 39400127, 2024). "In addition, our investigation revealed the geographical co‐localisation of CD14+APOE+ cells and MMP7+ tumour cells, and examined the intercellular communication between these two cell types." (PMID 39187937, 2024). "The commercial tumor dissociation kit is for purifying tumor cells from tissues, which was reflected in our tests as the tumor dissociation kit had higher proportions of CD45- cells and lower proportions of CD14+ cells compared to the optimized protocol." (PMID 39682129, 2024). "A more targeted analysis of innate immune cell subsets revealed subsets of CD14+ macrophages (CD16+ CD68+ CD206+ CD11c+/–) were significantly higher within tumor compared with nontumor regions." (PMID 39761010, 2024). "Recent scRNA analysis revealed that CXCR4 was expressed in tumor infiltrates including myeloid cells as well as T-cells and B-cells in the TME, suggesting that CD14 TAMC uniquely may be accompanied by lymphocytes marked by CXCR4." (PMID 38557819, 2024). "Notably, these markers have previously been linked to different cell types, including endothelial cells (CD44, ENG, F3, MCAM, and ITGB1), immune cells (CD14, CD44, CSPG4, ENG, HLA-DR/DP/DQ), and neuronal cells (NCAM1), as well as astrocytes and tumor cells." (PMID 39594703, 2024). "Conversely, stromal regions were associated with a substantial abundance of lineage-defining immune markers (CD3, CD8, CD4, CD20, CD14, CD11C), confirming a complex, but tumor-excluded immune environment prior to treatment in most patients regardless of response status." (PMID 39638782, 2024). "We observed decreased CD1c+CD14+ DC frequencies in patients within 10 weeks after NSCLC resection, supporting the hypothesis of a tumor-driven emergence of CD1c+CD14+ DCs." (PMID 38242119, 2024). "Moreover, to determine the relative uptake of TDEV when tumour cells were present, PKH-26 labelled TDEV were added to tumour:PBMC co-cultures, and the percentage of TDEV positive tumour (CD45-) and CD14+ cells was assessed using flow cytometry." (PMID 39763667, 2024). "Of note, Zilionis and co-workers use the term “DC3” in NSCLC for mature tumor-infiltrating DCs lacking CD14 expression, which do not correspond to the tumor-induced CD1c+CD14+ cells described here." (PMID 38242119, 2024). "The higher expression of the co-stimulatory molecule and M1 marker CD40 on CD45/CD14+ cells in the 4-culture PANC-1 spheroids could explain the therapeutic effect of CD40 ligand/agonists in the treatment of PDAC, boosting an anti-tumor response." (PMID 37519820, 2023). "However, CD3+, CD16+CD56dim NK cells, CD14+HLADRhigh monocytes, and CD8+ cells were found to decrease when the patient experienced the tumor progression." (PMID 37638022, 2023). "hSIRPα is indeed expressed on human CD14+ macrophages in the bone marrow and tumor of HIS-MITRG mice, whereas it is not expressed on mouse F4/80+ macrophages." (PMID 38162643, 2023). "The expression of CD14 + and CD163 + cells was found to be in between tumor cells." (PMID 37061716, 2023). "The recruitment and polarization of CD14+ monocytes into the suppressive PD-L1+M2-like macrophages (co-expressing CD14 and/or CD163) by primary tumor cells (possibly via the secretion of CCL2) prevent the antigen presentation and immune response in the lymphatic niche." (PMID 36905477, 2023).
tumor (continued). "Tumor derived exosomes have the ability to alter monocytes differentiation, which leads to the formation of immunosuppressive CD14+ HLA-DRlo/neg monocytes, characterized for the absence of HLA-DR and costimulatory molecules." (PMID 37915578, 2023). "Using the TCGA and GTEx data, we could learn the expression of five genes of the TEXPM construct, FTL, GZMA, CD14, and NPC2 were highly expressed in tumor tissues, and IER3 was highly expressed in paracancerous tissues." (PMID 37354485, 2023). "LAIR-1 was multiplexed with lymphocyte markers (CD45RA, CD4, CD8, CD20, CD56), myeloid monocyte markers (CD14, CD68, CD163 for macrophages and CD66b for neutrophils), fibroblast marker (SMA), hematopoietic progenitor cells (HPC, CD34) and tumor marker (pan CK)." (PMID 36960400, 2023). "Four macrophage subclusters were annotated, including a CD14+MSR1+CD163-cluster (MA1) that were mainly found in samples collected from the primary tumor site (ovary) and thus not seen in our previous study." (PMID 38328306, 2023). "The expression of CD14 (monocyte and macrophage marker) showed opposite trends from the expression of KRT19 (malignant cells marker), suggesting that monocytes or macrophages were enriched in normal regions compared with tumour regions." (PMID 37401015, 2023). "Moreover, the presence of CD11b+/CD14−/CD15+/CD33+ granulocytic‐MDSCs and CD14+/S100A9+ monocytic‐MDSCs, expressing L‐arginase and nitric oxide synthase, in the tumor area, resulted in suppression of CD8+ T cells and correlated with reduced survival." (PMID 35035956, 2022). "Our future efforts will focus on ex vivo tumor samples, where they will be incubated with the three recombinant proteins, sectioned, and stained for different cell types and quantifying their expression, e.g., vimentin, α-SMA, CD8, CD14." (PMID 36361532, 2022). "There were three types of tumor associated monocyte/macrophages, namely, the classical (CD14+; CD16−), the non-classical (CD16+), and the intermediate tumor associated monocyte/macrophages (CD14+; CD16+)." (PMID 35692828, 2022). "This aspect may be explained by the presence of a saturation effect, which means that a limited number of CD14+/CD16+ monocytes can phagocytize TKTL1 and Apo10 expressed by the tumor cells in patients with advanced stage disease." (PMID 36009359, 2022). "Single-cell dataset revealed an enrichment of multiple efferocytosis-related genes in distinct myeloid subsets within the tumor, specifically, SPP1+, ISG15+, C1QC+ macrophages, and CD14+ monocytes in the tumors, which were distinct from the scRNA-Seq from the peripheral blood." (PMID 36439171, 2022). "The results found that the expression levels of ABCG1, HAVCR2, CD14, and TGFA were significantly increased (p < 0.05) in tumor tissue samples compared with para-cancerous control tissue samples, while the expression levels of KDF1 and KITLG were significantly decreased (p < 0.05)." (PMID 35774505, 2022). "However, higher levels of CD14+CD16+ monocytes were shown in early-stage BC patients, especially those with stage I and/or small tumor size (T1–T2) in comparison with stage II-IV patients." (PMID 36358879, 2022). "In addition to the lymphoid lineage markers including CD3, CD4, CD8, CD20, CD45, CD56, and FOXP3, we also examined myeloid lineage markers such as CD14, CD68, CD34 to accurately identify the specific cell types within the tumor microenvironment of YTMA-76." (PMID 35810563, 2022). "Initially, the presence of CD4 and CD56 should be evaluated since only 8% of BPDCNs are negative for these, and their mere presence without other specific lineage markers such as CD19, cCD3, MPO, CD14, or CD64 with high HLA-DR should alert about the possibility of this type of neoplasm." (PMID 35530883, 2022). "On the one hand, CD14 could activate TLR-Myd88-NFκB and MyD88–CD14–IRAK1 pathway to promote tumor growth." (PMID 35387121, 2022).
tumor (continued). "We observed that the expression of human CD14, a myeloid cell marker, was significantly higher in MKN74 tumours at baseline, indicating that immune cells at baseline may not be T cells, but myeloid cells." (PMID 36071036, 2022). "One emerging mechanism of CD14+-cell-mediated tumor survival, not related to immunosuppression, is improved tumor resistance to local environmental stresses, such as chemotherapy or other systemic therapy." (PMID 36139660, 2022). "Through enlarging patient samples, we verified the increase in the CA12 mRNA level in tumor-infiltrating monocytes and found that other CD14– cellular components did not express CA12 in either tumor tissues or nontumor liver tissues." (PMID 35362480, 2022). "Previously, we found that CD14+ cells highly infiltrate the tumor microenvironment of IBC compared to non-IBC patients." (PMID 35847899, 2022). "Importantly, the mRNA expression levels of CA12 and GLUT1 showed positive correlation in TSN-treated CD14+ cells at early culture, similar to the correlation observed in their HCC tumor–purified counterparts." (PMID 35362480, 2022). "Although these variances induce mostly anti-tumor response, a wide range of dysregulated survival signals and absence of regulatory proteins such as CD14 support tumor progression through M2 polarization and invasiveness." (PMID 35486660, 2022). "Next, we employed lineage-specific markers to annotate clusters into major cell types of the tumor, including T cells (CD3G, CD4, CD8A, CD28, and IL7R), B cells (CD19 and CD20), myeloid cells (HLA-DRA and CD14), fibroblasts (THY1 and ACTA2), and tumor cells (EPCAM and S100A)." (PMID 35634306, 2022). "Lower levels of SIGIRR and of TOLLIP, NFRKB, TNFRSF1A, and CD14 and of two distinct MAP kinases were detected in all the cancer cell lines analyzed; on the contrary, IRAK1 and HSPD1 mRNAs were upregulated in all the tumor cells." (PMID 35814450, 2022). "Regarding CD14 cells, our results suggest that IMC tumour cells are more antigenic than MC tumour cells and thus recruit a greater number of inflammatory cells to the tumour site." (PMID 35512031, 2022). "To explore whether CA12 facilitates tumor metastasis by regulating the production of CCL8 in monocytes, we treated CD14+ cells from healthy donors with HepG2 TSN in the presence or absence of the glycolysis inhibitor 2DG, CA12 inhibitor, or siCA12." (PMID 35362480, 2022). "As macrophages (defined as CD14+CD11b+) constitute a major TNF-producing cell subpopulation and were the dominant CD16+ cell subset in the CRC tumor suspensions, the observed increase in TNF levels could be macrophage-derived." (PMID 34771609, 2021). "While patient 1′s tumor showed the presence of several CD45+ cell subsets regardless of the dissociation method, the tumors of patients 2 and 3 only showed cell expression of CD14+ leukocytes and HLA-DR positive cells, respectively." (PMID 33670410, 2021). "We also find that the STK11, CD14, and BRD7 genes in the manatee were also well conserved, suggesting that extant manatees may also have enhanced tumor suppression and an augmented stress response." (PMID 33513090, 2021). "There was a negative correlation between stromal CD33+ cells and CD14 expression in the tumor stroma (r = -0.303, p = 0.0073)." (PMID 33625532, 2021). "Indeed, DCs acquire an immunosuppressive phenotype (CD14+/CD16+/CD68+/CD124+/CD209+; PD-L1 overexpression), becoming incapable of cross-presenting tumor antigens to T cells and inhibiting the T cell response." (PMID 34945784, 2021). "Compared with the NC tumours, the protein level of CD11b and CD14 greatly increased in ZEB1 knock‐down tumours, while the expression of cyclin D1, cyclin A2, p‐Rb and CDK4 was markedly decreased in ZEB1 knock‐down tumours." (PMID 33960640, 2021). "YFP+ tumor cells expressed neither Tlr2 nor Cd14 and expressed little Tlr4, indicating that, in vivo, they are also unlikely to signal upon TLR2-TLR4 ligation." (PMID 34032639, 2021).
tumor (continued). "The markers synaptophysin, PCNA, DAXX, laminin and CD14 had similar expression levels in tumour and non-tumour tissue." (PMID 33906633, 2021). "In parallel, our multiplex immunofluorescent staining also showed a concordant increase in the number of CD4+ and CD8+ T cells per mm2 of tumor section in GBM.pembro patients compared to GBM.rec patients, while the number of CD14+ myelo-monocytic cells was similar." (PMID 34836966, 2021). "CD14+, CD68+ and CD163+ cell densities in the intratumoral tumor (IT tumor) compartment (p = 0.001; p < 0.001 and p = 0.004, respectively) and peritumoral tumor (PT Tumor) compartment (p = 0.001; p = 0.003 and p < 0.001, respectively) differed between grades of differentiation." (PMID 34194435, 2021). "Moreover, it was recently found that CCL15 induced the recruitment of CCR1+ CD14+ monocytes to HCC invasive margin; in turn, monocytes suppressed the anti-tumor immune response and promoted tumor metastasis." (PMID 31991677, 2020). "Moreover, CD14 and TLR4 expression involved in endotoxin signaling was downregulated in PBMCs and tumor-derived cells." (PMID 32425932, 2020). "Intracellular staining of tumor-related markers such as Apo10 and TKTL1 can be considered as a methodology using the circulating CD14+CD16+ myeloid cells in the blood, which may provide information on the tumor." (PMID 32438648, 2020). "Giving their clinical relevance in different tumour types, we next evaluated whether direct tumour influence in the OMC could convert immunocompetent cDC2s into CD14+ DCs." (PMID 32488012, 2020). "AR was expressed in a median of 32.9% of CD163 and/or HLA-DRA and/or CD14 expressing cells in the Tumour area, which was not significantly different from cells in the tumour border or in the distant area (median 34.2% and 35.2%, respectively)." (PMID 32908142, 2020). "As an example, all the tumor cells within the PyMT model correspond to the LP cell state and in such a scenario CD14 is not differentially expressed between the tumor cell clusters." (PMID 32840210, 2020). "MDSCs constituted about 5% of the cells within GBM tumor masses and where depicted with obvious CD33+/CD15−/CD14−/HLA-DR− negative lineage subsequent to CD33+/CD15+/CD14−/HLA-DR− neutrophilic as well as CD33+/CD15−/CD14+/HLA-DR− monocytic subtypes." (PMID 33204365, 2020). "Conversely, we found a higher percentage of CD14+ TREM-2+ monocytes in better surviving patients; these cells could downregulate the exaggerated inflammation and potentiate the phagocytosis in the tumor." (PMID 32684831, 2020). "Interestingly, increased frequency of both M-MDSCs (HLA-DR−/lowCD11b+CD14+CD15−) and G-MDSCs (HLA-DR−/low CD11b+CD14− CD15+) has been found not only in the peripheral blood of patients but also in the tumor lesions." (PMID 32849585, 2020). "Single immune cells were detected with trained algorithms in annotated tumor, invasive margin and normal colon ROI and cell densities of CD11b+CD14+, CD11b+CD15+ and ARG1+ myeloid cells, and CD8+Ki67+/–, CD8+Ki67+/– and FOXP3+ T cells were computed respectively." (PMID 33193316, 2020). "After treatment-induced tumor regression, CD14+ cells from the same patients did not express PD-Ls, failed to produce cytokines, and recovered tumoricidal activity." (PMID 32824016, 2020). "We found a higher percentage of CD14+ TREM-2+ monocytes in better surviving patients; these cells could downregulate the exaggerated inflammation and potentiate the phagocytosis in the tumor." (PMID 32684831, 2020). "CD14 trogocytosis was detected although at a lesser extent, likely due to the fact that not all tumor cells express CD14." (PMID 33276644, 2020). "In the tumor ROI, we focused on stromal and epithelial tumor compartments and assessed their infiltration by monocytic CD11b+CD14+, granulocytic CD11b+CD15+, and immunosuppressive ARG1+ myeloid cells and also CD8+Ki67+/– cytotoxic and FOXP3+ regulatory T cells." (PMID 33193316, 2020).